HOTAIR (HOX transcript antisense RNA)
Synonyms: HOXC-AS4; HOXC11-AS1; NCRNA00072; HOXAS
Gene: Long non-coding RNA gene on chromosome 12 (53,962,308 to 53,975,055, reverse strand). Ensembl gene ENSG00000228630.
Gene Ontology:
Biological process: heterochromatin formation
Diseases named in the same sentence as HOTAIR in open-access papers:
HOTAIR is named in the same sentence as 253 diseases in open-access papers, as found by Europe PMC text mining. Sharing a sentence is not in itself a finding about the gene and the disease. The quoted sentences say what the papers report.
breast cancer (408 papers, 2011 to 2026). A primary or metastatic malignant neoplasm involving the breast. "Higher levels of HOTAIR expression in breast cancer tissues are associated with more aggressive tumor behavior and a poorer prognosis." (PMID 39858015, 2025). "Dysregulated expression of HOX anti-sense intergenic RNA (HOTAIR) is associated with different cancers like breast cancer, liver cancer and lung cancer." (PMID 39940704, 2025). "High HOTAIR expression is associated with poor prognosis and resistance to DNA-damaging therapies in breast cancer." (PMID 39997609, 2025). "For instance, lncRNA HOTAIR has been implicated in the progression of breast cancer through its interaction with the Polycomb repressive complex 2 (PRC2), which facilitates the silencing of tumor suppressor genes via histone modification." (PMID 40149989, 2025). "This study aims to investigate the HMGA2 associated HOTAIR pathway, which has been implicated in carcinogenesis in breast cancer patients, at the molecular level and to evaluate its clinical significance." (PMID 40686703, 2025). "For example, research on the HOTAIR gene has shown that specific polymorphisms, such as rs920778 and rs12826786, are significantly linked to breast cancer susceptibility and clinicopathological features in Turkish populations." (PMID 40158114, 2025). "Among the most studied lncRNAs in breast cancer are HOTAIR, UCA1, and MALAT1, which have been strongly implicated in tumorigenesis, metastasis, and therapy resistance." (PMID 40781106, 2025). "Previous studies have shown that high expression of HOTAIR in cancers, such as breast cancer and lung cancer, is closely associated with tumor invasiveness, drug resistance, and poor prognosis." (PMID 40235720, 2025). "Increased HOTAIR expression in tumors of breast cancer cases is associated with a lower risk of relapse and mortality compared to those having low expression of HOTAIR in their cancers." (PMID 39329990, 2024). "In breast cancer and colorectal cancer, the upregulation of HOTAIR has been associated with the downregulation of miR‐193a expression." (PMID 39347925, 2024). "In PrognoScan database, the results revealed that HOTAIR expression associated with prognosis in colorectal and breast cancers." (PMID 38696320, 2024). "High levels of HOTAIR expression have been linked to poor clinical outcomes and a poor prognosis of patients with breast cancer." (PMID 37795578, 2023). "Two other prominent examples of breast cancer linked lncRNAs are HOTAIR (HOX antisense intergenic RNA) and MALAT1 (Metastasis-associated lung adenocarcinoma transcript 1)." (PMID 37990044, 2023). "HOTAIR is a well-studied lncRNA, that is associated with a poor prognosis, recurrence, and metastasis of breast cancer, pancreatic cancer, gastric cancer, and other cancers 29-32." (PMID 37576402, 2023). "It was observed that there are many different mechanisms of interplay between autophagy and HOTAIR in breast cancer; however, further research is required to find the underlying mechanisms." (PMID 36899946, 2023). "A high expression of HOTAIR in breast cancer has also been directly linked to increased metastasis and drug resistance." (PMID 37509693, 2023). "The overexpression of HOTAIR in several types of human cancers, including breast cancers has been linked to poor survival and increased metastasis." (PMID 36579891, 2022). "High levels of HOTAIR are associated with poor survival and more aggressive breast cancers in xenograft models." (PMID 36579891, 2022). "Studies have shown that HOTAIR induces invasion of breast carcinoma cells, and high HOTAIR expression levels associate with poor prognosis in breast cancer." (PMID 36358625, 2022). "Of the multiple cancer-associated lncRNAs, HOTAIR (HOX antisense intergenic RNA) was among the most overexpressed in breast cancer." (PMID 36358625, 2022).
breast cancer (continued). "LncRNA HOTAIR overexpression was found in patients with breast cancer, and its overexpression was associated with metastasis and poor prognosis." (PMID 36338672, 2022). "As a result, a six-genomic instability-related lncRNA signature (U62317.4, MAPT-AS1, AC115837.2, EGOT, SEMA3B-AS1, and HOTAIR) was identified as the independent prognostic risk model for breast cancer patients." (PMID 35990656, 2022). "Specifically, it was discovered that secretion of TGF-β1 by cancer associated fibroblasts (CAFs) led to direct binding of SMAD2-4 to the promoter of HOTAIR in breast cancer cells thus causing its expression." (PMID 35788171, 2022). "Subsequently, HOTAIR has been associated with the metastasis of many types of cancers, including colorectal, pancreatic, lung, and breast cancers." (PMID 36273585, 2022). "Abnormal overexpression of HOTAIR in cancer was first identified in breast cancer (BC) and has been associated with metastasis and poor survival." (PMID 36100611, 2022). "To determine the effect of the A783U mutation on HOTAIR-mediated breast cancer cell growth, we measured the doubling time of MDA-MB-231 cells expressing WT and A783U mutant HOTAIR." (PMID 36441764, 2022). "A number of studies have identified the expression of lncRNA HOTAIR in the blood of breast cancer patients where it was associated with the high expression of ERBB2 (Receptor tyrosine-protein kinase)." (PMID 36685962, 2022). "A significantly low serum Nestin below 39.9 pg/mL and a higher percentage of the T/T homozygous variant allele of HOTAIR rs12826786 C>T were found in Egyptian patients with breast cancer." (PMID 33584136, 2021). "Generally, HOTAIR expression is significantly elevated in patients’ serum than in healthy ones, which can be regarded as a potential diagnostic biomarker of breast cancer." (PMID 34073224, 2021). "The study also aimed at evaluating the possibility of using Nestin and HOTAIR gene rs12826786 polymorphism as possible screening tools to identify patients with breast cancer." (PMID 33584136, 2021). "Several SNPs of HOTAIR, including rs12826786, rs920778, rs1899663, and rs4759314, have determined that they are linked to breast cancer susceptibility and other clinical values." (PMID 34073224, 2021). "The altered lncRNAs in tumors are expected to be used as diagnostic markers in multiple tumors, such as lncRNA HOTAIR (in breast cancer) and lncRNA MALAT1 in liver cancer, breast cancer, non-lung small cell carcinoma, colon cancer and prostate cancer." (PMID 34399848, 2021). "The current study also found a significant association between the HOTAIR rs12826786 C>T polymorphism and breast cancer in Egyptian women." (PMID 33584136, 2021). "Estrogens like estradiol induce the expression of HOTAIR gene via ERα response element and cause the progression of sex hormone-dependent cancers like breast carcinoma." (PMID 35178360, 2021). "Studies have shown that different HOTAIR variants (e.g., rs920778, rs7958904, and rs874945) correlate with different cancers, including GC, colorectal cancer, breast cancer, and esophageal cancer." (PMID 33028884, 2020). "For example, the augmented expression of the lncRNA HOTAIR is associated with metastasis in breast cancer patients, suggesting its unique link with the patient prognosis." (PMID 32929060, 2020). "In this review, we aim to briefly outlook the role of HOTAIR in breast cancer progression, as a new potential diagnostic and prognostic biomarker." (PMID 32245498, 2020). "Consistently, high expression of HOTAIR is associated with a short duration of metastasis-free and overall survival in patients with breast cancer." (PMID 32486413, 2020). "HOTAIR, a non‐coding RNA first discovered in breast cancer, is associated with metastasis and poor prognosis of breast cancer." (PMID 33145980, 2020).
breast cancer (continued). "A clinical study suggested that high HOTAIR expression in breast cancer was significantly associated with poor prognosis, particularly in patients with estrogen receptor (ER)-positive tumors." (PMID 32104724, 2020). "Related studies have found that breast cancer patient’s tumor tissue and plasma had high expression of HOTAIR, HOTAIR diagnostic efficacy and specificity is high and can be used as a potential diagnostic marker for breast cancer." (PMID 30828265, 2019). "Out of cancer-associated lncRNAs, HOTAIR (HOX antisense intergenic RNA) is the most up-regulated in breast cancer." (PMID 30429228, 2019). "The functional characteristics of certain lncRNAs, such as UCA1, GAS5, and XIST, have established them as breast cancer‐associated tumor suppressors, while HOTAIR, TINCR, and DSCAM‐AS1 are known as oncogenic lncRNAs." (PMID 30959550, 2019). "Some of these lncRNAs have been shown to be associated with the development of breast cancer, such as HOTAIR, UCA1, and LINC00518,30, 31 but the research on the role of lncRNAs in breast cancer is still very scarce." (PMID 30932362, 2019). "HOTAIR is also an independent biomarker for predicting the risk of metastasis and mortality in breast cancer with high expression levels of HOTAIR correlating with decreased prognosis." (PMID 29732012, 2018). "To further assess the suggestive association between HOTAIR polymorphisms and the risk of breast cancer, we conducted stratified analyses among different subgroups of demographic characteristics and reproductive factors in dominant model." (PMID 29423075, 2018). "In this present study, we evaluated the effects of three potential functional HOTAIR polymorphisms (rs1899663, rs4759314 and rs7958904) on breast cancer susceptibility and clinical outcomes in a Chinese population." (PMID 29423075, 2018). "Recently, several single nucleotide polymorphisms located in HOTAIR were also reported to show highly significant associations with breast cancer." (PMID 29423075, 2018). "The relevance of HOTAIR in cancer was first reported by an association between HOTAIR expression and increased metastatic potential and diminished survival of breast cancer patients." (PMID 29644006, 2018). "And to the best of our knowledge, this is the first study to evaluate the correlations between HOTAIR variants and breast cancer survival." (PMID 29423075, 2018). "The oncogenic roles of HOTAIR have attracted extensive attentions in breast cancer, while epidemiological studies focusing on tumor susceptibility and prognosis conferred by genetic polymorphisms in its locus have not been widely investigated." (PMID 29423075, 2018). "In breast cancer patients high circulating HOTAIR level is also associated with lymph node metastasis." (PMID 30541551, 2018). "Our data indicate that HOTAIR overexpression is associated with highly expressed Bcl-w in breast cancer." (PMID 29222472, 2017). "The role of HOTAIR-mediated autophagy in breast cancer progression can be underlined by its interaction with matrix metalloproteinases, essential for cancer invasion, and β-catenin can be important for this interaction." (PMID 29469819, 2017). "lncRNA HOTAIR has been reported to be upregulated in breast cancer, pancreatic cancer, lung cancer, and gastric cancer, and high HOTAIR expression is associated with poor prognosis." (PMID 28938565, 2017). "A total of four articles reported the effects of HOTAIR polymorphisms in gastric cancer, two in breast cancer, one in oesophageal squamous cell carcinoma (ESCC), and one in colorectal cancer." (PMID 27010768, 2016). "The lncRNA HOTAIR is overexpressed in tamoxifen-resistant breast cancer compared to their primary counterparts, and is associated with poor clinical outcomes." (PMID 27897214, 2016). "In breast cancer patients, HOTAIR overexpression is associated with increased metastasis and reduced overall survival." (PMID 26992233, 2016).
breast cancer (continued). "One example of such oncogenic lncRNA is HOTAIR, which is highly expressed in breast cancer and is a predictor for metastasis formation and associated with a poor prognosis." (PMID 27172249, 2016). "Aberrant expression of HOTAIR has been associated with tumorigenesis in various types of cancer including breast cancer, colorectal cancer, non-small cell lung cancer, liver cancer." (PMID 27895308, 2016). "In summary, HOTAIR level is increased in breast cancer patients and associated with cancer migration." (PMID 25928008, 2015). "Overexpression of HOTAIR has been associated with enhanced metastasis and invasion of breast cancer cells and can be used as a predictor of overall survival and progression-free survival." (PMID 25849966, 2015). "HOTAIR was the first lncRNA shown to promote tumor progression and is associated with poor prognosis in breast cancer." (PMID 25883211, 2015). "Recently, the lncRNA HOTAIR was associated with metastatic progression in human breast cancer, hepatocellular carcinoma, cervical and pancreatic cancer." (PMID 25405331, 2015). "One notable example is HOTAIR, which is over-expressed in breast cancers; loss of HOTAIR reduces the invasiveness of breast cancer." (PMID 25739977, 2015). "HOTAIR up-regulation is associated with poor prognosis in breast cancer, liver, colorectal, gastrointestinal and pancreatic cancers." (PMID 25276098, 2014). "Loss of HOTAIR moderates the invasiveness of breast cancer, particularly in cells in which polycomb repressive complex 2 (PRC2) is up-regulated." (PMID 25334066, 2014). "HOTAIR, a prominently focused lncRNA, was initially reported to be implicated in primary breast cancer and breast cancer metastasis, wherein elevated HOTAIR promoted tumor invasiveness and metastasis." (PMID 25303230, 2014). "HOTAIR upregulation is associated with poor prognosis in breast cancer, liver, colorectal, gastrointestinal and pancreatic cancers and probably contributes to increase also tumor invasiveness and metastasis." (PMID 24129177, 2013). "Overexpression of HOTAIR lncRNA was found in several solid tumors in association with cancer metastasis, and increased HOTAIR expression in breast cancer is transcriptionally induced by estradiol." (PMID 24222893, 2013). "In a retrospective clinical study, HOTAIR overexpression in estrogen receptor positive (ER+) breast cancer patients was strongly associated with metastatic risk, suggesting that it may be a potential prognostic biomarker." (PMID 40686703, 2025). "HOTAIR has also been reported to be involved in epigenetic mechanisms underlying breast cancer." (PMID 40686703, 2025). "Additionally, HOTAIR has been associated with PI3K/AKT pathway regulation in breast cancer, retinoblastoma, and gastric cancer via microRNA regulation." (PMID 39273054, 2024). "Furthermore, the HOTAIR rs920778 polymorphism is associated with worse progression-free survival in breast cancer patients and colorectal cancer mortality." (PMID 38339237, 2024). "In addition, the HOTAIR rs920778 T allele contributes to an increased risk of head and neck cancer of esophageal origin, breast cancer in the Chinese and Iranian populations, as well as gastric cancer and colorectal cancer." (PMID 38339237, 2024). "HOTAIR has been particularly associated with metastasis in breast cancer." (PMID 37108589, 2023). "Furthermore, a loss of HOTAIR function is sufficient to prevent cell invasion and metastasis in breast cancer, reflecting the role of this lncRNA as a potent oncogene and pointing it out as a possible therapeutic target." (PMID 35054945, 2022). "HOTAIR can regulate gene expression epigenetically in a manner similar to scaffolding and can also interfere with the expression of signaling molecules associated with breast cancer development in breast cancer." (PMID 36233075, 2022).
breast cancer (continued). "Originally identified as a developmental regulator acting in trans to repress expression of the HoxD locus, aberrant high levels of HOTAIR are associated with poor survival and increased cancer metastasis in many different cancer types, including breast cancer." (PMID 36441764, 2022). "In addition, these studies reported that high HOTAIR expression is associated with ER and PR positivity, and HOTAIR expression is a strong predictor of poor clinical outcome, especially in ER+ breast cancer." (PMID 36358625, 2022). "Also, while one specific m6A site at A783 is important for mediating chromatin association and the physiological effects of HOTAIR in breast cancer, other m6A sites play a role in overall expression or stability." (PMID 36441764, 2022). "Future work will concentrate on reproducing the reported results in a bigger cohort of the breast cancer group to investigate serum Nestin and HOTAIR gene polymorphism in different subgroups of breast cancer patients according to their histopathological and molecular subtype." (PMID 33584136, 2021). "Some studies reveal HOTAIR to be a diagnostic biomarker in breast cancer." (PMID 34073224, 2021). "For example, the H19 gene induced the epithelial to mesenchymal transition (EMT) in colorectal cancer; HOTAIR expression is closely associated with breast cancer metastasis and the high expression of HOTAIR is a powerful predictor of eventual metastasis and death." (PMID 32714183, 2020). "Here, we highlighted the impact of unfitting expression of HOTAIR in the survival and progression of breast cancer cells; in some cases, we also implicated the role of HOTAIR in other types of cancer to elucidate potential role of this lincRNA in breast cancer." (PMID 32245498, 2020). "However, the artificial chromatin tethering of HOTAIR in breast cancer cells caused transcription repression independently of PRC2." (PMID 33291485, 2020). "Findings obtained from these studies raised the curiosity to navigate the cause(s) of this inconsistency on the mode of HOTAIR expression in the breast cancer patients’ circulating and peripheral blood mononuclear cells compared to the observed results in our experiment." (PMID 31796041, 2019). "However, the underlying mechanism of HOTAIR in breast cancer development need to be further investigated." (PMID 29222472, 2017). "Importantly, loss of HOTAIR resulted in a decreased invasiveness of breast cancer cells, especially in cells with overactive PRC2." (PMID 29469819, 2017). "Moreover, the levels of HOTAIR were positively associated with those of Bcl-w in clinical breast cancer samples." (PMID 29222472, 2017). "Consequently, HOTAIR can be an important regulator of gene expression in breast cancer associated with BRCA1 mutations." (PMID 29469819, 2017). "Finally, an important gene at the HOXC locus involved in PRC2-mediated repression is HOTAIR, which encodes a large intervening noncoding RNA (lincRNA) associated with breast cancer prognosis." (PMID 26029238, 2015). "The LncRNAs such as up-regulation of HOTAIR could be associated with poor prognosis in breast cancer, liver, colorectal, gastrointestinal and pancreatic cancers." (PMID 25276098, 2014). "As the research in this area has progressed, numerous HOTAIR-related studies have been published, and aberrant expression of HOTAIR has been associated with cancers at various sites, including lung cancer, cervical cancer, breast cancer, glioblastoma, and gastrointestinal cancers." (PMID 36924407, 2023). "Golshan and colleagues, indeed, described that the treatment of breast cancer cells with metformin, a hypoglycemic drug well-known for its anticancer properties, promotes the methylation of a CpG-rich sequence located at the downstream region of HOTAIR gene, causing its downregulation." (PMID 37308974, 2023). "However, the underlying mechanism of HOTAIR in breast cancer requires more research." (PMID 36233075, 2022).